RIT1 (Ras like without CAAX 1)
Diseases named in the same sentence as RIT1 in open-access papers (continued):
Sharing a sentence is not in itself a finding about the gene and the disease.
lung carcinoma (6 papers, 2018 to 2025). "RIT1 mutations are mutually exclusive with other lung cancer drivers and lack targeted therapies." (PMID 34373451, 2021). "The role of RIT1 activation is a less well-understood part of the RTK-RAS signaling pathway in lung cancer." (PMID 34373451, 2021). "We previously demonstrated that RIT1M90I and other RIT1 variants, as well as KRASG12V, confer resistance to EGFR targeted therapy in EGFR-mutant lung cancer cells." (PMID 34373451, 2021). "This study expands our knowledge of EGFR/RAS signaling in lung cancer and provides a genome-wide discovery of factors that cooperate with or antagonize oncogenic RIT1." (PMID 34373451, 2021). "Data from The Cancer Genome Atlas also show that RIT1 were overexpressed in pancreatic carcinoma, lung carcinoma, and tongue squamous cell carcinoma tissues." (PMID 30348939, 2018). "In addition, we identify many other candidate EGFR-, KRAS-, and RIT1 dependencies that should be further explored as drug targets for lung cancer therapy." (PMID 34373451, 2021). "In this work, to investigate the structure of the EGFR/RAS/RIT1 signaling network and identify therapeutic targets in lung cancer, we perform genome-wide CRISPR screens in isogenic PC9 cells where drug resistance is potently conferred by each expressed oncogene." (PMID 34373451, 2021). "Finally, we included 10 well-known cancer-related genes (or their hotspot-containing exons) listed as most frequently mutated in lung cancer (BRAF,EGFR,ERBB2,HRAS,KRAS,MAP2K1,MET,NF1,NRAS, and RIT1) in the panel to serve as internal controls for highly mutated regions." (PMID 40867048, 2025). "From a therapeutic perspective, the reduction of RIT1 may provide benefits in lung cancer therapy with or without LZTR1 mutations." (PMID 37626065, 2023). "Furthermore, we identify YAP1 activation as a key cooperating event in RIT1-mutant lung cancer." (PMID 34373451, 2021). "The finding of nuclear YAP1 staining in human RIT1-mutant tumors suggests that RIT1 variants may be most oncogenic in the context of YAP1 activation, and therefore targeting YAP/TEAD activity should be explored as a strategy to suppress RIT1-mutant lung cancer." (PMID 34373451, 2021). "Consistent with this idea, mutant RIT1 can transform NIH3T3 fibroblasts and confer resistance to EGFR inhibition in EGFR-mutant lung cancer cells." (PMID 34373451, 2021). "Supporting a requirement for RIT1, AURKA, IGF1R, and FURIN in the proliferation of RIT1-mutant lung cancer, knockout of each gene significantly reduced cell proliferation of H2110iCas9 compared to cells expressing a non-targeting control guide (sgNTC)." (PMID 34373451, 2021). "A disadvantage of the experimental system, however, was its reliance on treatment with erlotinib, which would not typically be used for the treatment of RIT1-mutant lung cancers." (PMID 34373451, 2021).
hepatocellular carcinoma (5 papers, 2018 to 2024). A malignant tumor that arises from hepatocytes. "Previous studies showed that RIT1 was overexpressed in about 25% of patients with hepatocellular carcinoma, due to amplification and occasionally mutation." (PMID 30348939, 2018). "Our previous study has demonstrated the involvement of RIT1 in promoting malignant progression of hepatocellular carcinoma (HCC)." (PMID 38017479, 2023). "The RIT1 gene was amplified, which may be one of the activation ways in hepatocellular carcinoma." (PMID 37215053, 2023). "Excessive activation of RAS/MAPK signaling is commonly observed in hepatocellular carcinoma (HCC), and it has been found that RIT1 induces angiogenesis through the MEK/ERK/EIF4E/HIF1-α/VEGFA axis." (PMID 36941564, 2023).
leukemia (5 papers, 2017 to 2025). A malignant (clonal) hematologic disorder, involving hematopoietic stem cells and characterized by the presence of primitive or atypical myeloid or lymphoid cells in the bone marrow and the blood. "Studies have shown that RIT1 mutations are also common in acute myeloid leukaemia, which can enhance leukaemia cell survival and proliferation, further exacerbating the disease." (PMID 39833023, 2025). "Consistently, Leukemia-associated RIT1 mutations, which stabilize RIT1 proteins, strongly enhance the self-renewal of hematopoietic stem cells and leukemia progression." (PMID 38017479, 2023).
cardiac hypertrophy (4 papers, 2022 to 2025). "Rit1 mutation causes cardiovascular and lymphatic abnormalities in the fetal period, and that the activation of MEK/ERK is the potential pathogenesis of cardiac hypertrophy." (PMID 41388936, 2025). "In a preclinical trial using a Rit1 mouse model of NS, treatment with trametinib prevented progression of cardiac hypertrophy, as determined by heart weight and myocyte size." (PMID 35266292, 2022). "Richard Van, BS, and Morgan Wagner, BS, presented a biochemical analysis of RIT1, which revealed preferential interaction at the plasma membrane with RAF1 and provided evidence for therapeutic intervention of cardiac hypertrophy." (PMID 35266292, 2022).
cardiomyopathy (4 papers, 2019 to 2024). A disease of the heart muscle or myocardium proper. "We identified further genes that regulate the development of trabeculation (NKX2-5, TBX20, HAND2, NRG1, NOTCH1 and DTNA) and those with evidence of involvement in cardiomyopathies (CRYAB and RIT1 (ARHGEF2))." (PMID 39567769, 2024). "In addition, Gene Ontology (GO) and Kyoto Encyclopedia of Genes and Genomes (KEGG) analyses revealed an enrichment of genes critical for proper cardiac function and whose dysregulation may contribute to the cardiomyopathy-like phenotype exhibited by RIT1 NS murine models." (PMID 37450595, 2023).
Chylothorax (3 papers, 2022 to 2024). The presence of chyle in the thoracic cavity. "Postnatally, the prevalence of lymphedema differs from 16% in patients with pathogenic PTPN11 variants to 44% in patients with pathogenic SOS1 variants, and the prevalence of acquired chylothorax is 4% in patients with pathogenic RIT1 variants." (PMID 39229301, 2024).
atrial fibrillation (2 papers, 2022 to 2026). A disorder characterized by an electrocardiographic finding of a supraventricular arrhythmia characterized by the replacement of consistent P waves by rapid oscillations or fibrillatory waves that vary in size, shape and timing and are accompanied by an irregular ventricular response. "Case 1 is a middle-aged man presenting with atrial fibrillation and imaging evidence of right ventricular (RV) fatty infiltration, repolarization abnormalities, and positive signal-averaged electrocardiogram (ECG), in whom a pathogenic RIT1 variant was identified without desmosomal mutations." (PMID 41918562, 2026). "There was one SAE of atrial fibrillation reported in a 14‐year-old male patient who was PTPN11 negative and RIT1 positive, which has previously been described." (PMID 35245205, 2022).
atrial septal defect (2 papers, 2023 to 2025). Interauricular communication is a congenital malformation characterized by a communication between the atrial chambers of the heart. "The high incidence of HCM (50 to 70%) and related heart defects (pulmonary stenosis and atrial septal defects) in patients with RIT1 NS prompted us to establish an in vitro model system to investigate the impact of mutant RIT1 expression in cardiac cells." (PMID 37450595, 2023). "Four cases of atrial septal defects (ASD) and one case of ventricular septal defect were identified in ten Rit1A57G/+ embryos, whereas one case of ASD was observed in 11 Rit1+/+ embryos at E16.5." (PMID 41388936, 2025).
endometrial carcinoma (2 papers, 2018 to 2023). A malignant tumor arising from the epithelium that lines the cavity of the uterine body. "In endometrial cancer, elevated expression of RIT1 was associated with poor prognosis." (PMID 37215053, 2023). "Recent report showed that RIT1 was overexpressed in endometrial carcinoma and correlated with poorer prognosis." (PMID 30348939, 2018).
esophageal squamous cell carcinoma (2 papers, 2018 to 2023). Esophageal squamous cell carcinoma (ESCC) is a type of esophageal carcinoma (EC) that can affect any part of the esophagus, but is usually located in the upper or middle third. "In esophageal squamous cell carcinoma, RIT1 suppressed tumor cell growth and metastasis." (PMID 37215053, 2023). "However, the role of RIT1 in esophageal squamous cell carcinoma (ESCC) is unclear." (PMID 30348939, 2018).
LEOPARD syndrome (2 papers, 2023 to 2024). "This is also the case for 8/14 syndromic HCM (CACNA1C, FLNC, PRKAG2, PTPN11 (Noonan), PTPN11 (Noonan syndrome with multiple lentigines), RAF1, RIT1, TTR), 3/12 DCM (DES, TNNC1 and TNNT2), and 2/6 ARVC (JUP, TMEM43) gene-disease pairs." (PMID 37872640, 2023).
pulmonary stenosis (2 papers, 2018 to 2023). "In patients with RIT1 mutations, HCM (56%), atrial defects, and pulmonary stenosis are the more frequently reported clinical manifestations." (PMID 29402968, 2018).
pulmonary valve stenosis (2 papers, 2022 to 2025). The pathologic narrowing of the orifice of the pulmonary valve. "Patients with NS, particularly those with RIT1 variants, exhibit HCM and pulmonary valve stenosis (PS)." (PMID 41388936, 2025). "Among all the pathogenic variants, we found that patients with mutations in RIT1, SOS1, PTPN11, and SOS2 had common echocardiography figures characterized by pulmonary valve stenosis, while RAF1 patients had HCM." (PMID 35770001, 2022). "SOS1, RIT1, PTPN11, and SOS2 mutations showed common cardiac abnormalities such as pulmonary valve stenosis." (PMID 35770001, 2022). "RIT1, SOS1, PTPN11, and SOS2 had common echocardiography features characterized by pulmonary valve stenosis, while RAF1 was characterized by HCM." (PMID 35770001, 2022).
acute monocytic leukemia (1 paper, 2023). Acute monoblastic leukemia (AML-M5), is one of the most common subtypes of acute myeloid leukemia (AML) that is either comprised of more than 80% of monoblasts (AML-M5a) or 30-80% monoblasts with (pro)monocytic differentiation (AML-M5b). "In contrast, LZTR1 deficiency increased RIT1, KRAS, MRAS, and NRAS expression in fetal liver and acute monocytic leukemia cells." (PMID 37626065, 2023).
bleeding disorders (1 paper, 2021). "The mutational spectrum of patients with bleeding disorders was largely overlapping with that of the NS general population, including mutations in PTPN11, SOS1, RIT1, BRAF, and MAP2K1 genes." (PMID 34857025, 2021).
brain tumours (1 paper, 2025). "The IF for Ki‐67 was performed on the brain tumours, demonstrating that RIT1 knockdown led to reduced Ki‐67 expression relative to the control." (PMID 39833023, 2025).
breast carcinoma (1 paper, 2019). "To evaluate influence on PARP1 activity, we down-regulated the expression of RIT1, PSAT1 and INCENP by using siRNA and analyzed the level of PARylation in MCF7 breast cancer cell line." (PMID 31105872, 2019). "We decided to further validate RIT1, INCENP and PSTA1 in MCF7 breast cancer cells." (PMID 31105872, 2019).
chordoma (1 paper, 2025). Chordomas are rare malignant tumors arising from embryonic remnants of the notochord in axial skeleton. "Mechanistically, REGγ regulates chordoma progression through the ubiquitin- and ATP-independent degradation of RIT1, which modulates the RIT1-MAPK pathway." (PMID 41136369, 2025). "Inhibition of RIT1 in REGγ-knockdown cells and patient-derived organoids alleviated these effects, suggesting that targeting REGγ may be a promising strategy for chordoma treatment." (PMID 41136369, 2025). "Ras GTPases, including RIT1, are involved in cancer progression, and understanding their involvement in chordoma could provide therapeutic insights." (PMID 41136369, 2025).
Costello syndrome (1 paper, 2023). Costello syndrome (CS) is a rare multisystemic disorder characterized by failure to thrive, short stature, developmental delay or intellectual disability, joint laxity, soft skin, and distinctive facial features. "The remaining genes involved were RAF1 (three patients, all with Costello syndrome suspicion), RIT1 (two patients), BRAF (one patient), MAP2K1 (three patients), MAP2K2 (two patients), PTPN11 (two patients), SOS1 (one patient), and SHOC2 (three patients, two of them with Costello syndrome suspicion)." (PMID 37568403, 2023).
glioma (1 paper, 2025). A benign or malignant brain and spinal cord tumor that arises from glial cells (astrocytes, oligodendrocytes, ependymal cells). "Our findings indicate that RIT1 promotes glioma cell proliferation by activating PI3K/AKT/c‐Myc signalling." (PMID 39833023, 2025). "The flow cytometric analysis results demonstrated that RIT1 knockdown promotes apoptosis in glioma cells and inhibits cell cycle progression." (PMID 39833023, 2025). "This study demonstrates that RIT1 significantly contributes to the aggressive phenotype and unfavourable prognosis of glioma, indicating its ability as a therapeutic target for glioma treatment." (PMID 39833023, 2025). "Research findings showcased that RIT1 is significantly overexpressed in gliomas and exhibits a strong correlation with tumour grade and unfavourable clinical outcomes." (PMID 39833023, 2025). "Functional assays demonstrate that RIT1 facilitates the aggressiveness of glioma cells by activating the PI3K/AKT signalling." (PMID 39833023, 2025). "A gene pathway enrichment analysis was performed to clarify the molecular processes by which RIT1 promotes glioma cell growth." (PMID 39833023, 2025). "Our results align with those reported previously, showing that RIT1 promoted glioma growth, migration and invasion by activating PI3K/AKT signalling." (PMID 39833023, 2025). "Accordingly, we aimed to explore the role of RIT1 in glioma, explore new possible mechanisms that mediate glioma development, and provide new potential drug targets for subsequent treatment." (PMID 39833023, 2025). "The results from the WB analysis demonstrated that glioma tissues exhibited elevated expression levels of RIT1 compared to NBTs." (PMID 39833023, 2025). "This emphasises the promise of RIT1 as a therapeutic target for glioma and shows the necessity for more research to clarify its particular molecular mechanisms and assess its therapeutic relevance." (PMID 39833023, 2025). "This study employed quantitative reverse transcription PCR (qRT‐PCR), Western blotting (WB), immunohistochemistry (IHC) and additional methodologies to assess RIT1 expression levels in glioma tissues." (PMID 39833023, 2025). "In T98G and A‐172 cell lines, sh‐RNAs targeting c‐Myc were employed to further investigate its role in RIT1‐mediated glioma cell proliferation." (PMID 39833023, 2025). "The RT‐PCR was carried out foe additional investigation of RIT1 expression across different grades of human gliomas." (PMID 39833023, 2025). "Interestingly, we also found that RIT1 was inversely correlated with CD8+ T cells by analysing the glioma TCGA database." (PMID 39833023, 2025). "This indicates that RIT1 may augment the migratory and invasive properties of glioma cells, a defining trait of malignant tumours." (PMID 39833023, 2025). "Furthermore, the transwell assay results elucidated that RIT1 overexpression significantly augmented glioma cell invasion and migration." (PMID 39833023, 2025). "This suggests the potential utility of RIT1 as a prognostic glioma biomarker." (PMID 39833023, 2025). "Additionally, our experimental results demonstrated that RIT1 facilitates glioma aggressiveness by activating PI3K/AKT/c‐Myc signalling." (PMID 39833023, 2025). "In addition, higher glioma grades were positively related to RIT1 overexpression at the RNA and protein levels." (PMID 39833023, 2025). "The role of PI3K/AKT signalling has been reported in glioma development and chemotherapy resistance, but whether RIT1 mediates its activation remains unknown." (PMID 39833023, 2025). "Interestingly, we also found through analysis of the TCGA database that HIF‐1α and RIT1 are positively correlated in glioma tissues." (PMID 39833023, 2025). "The results demonstrated that RIT1 expression levels varied among different glioma grades." (PMID 39833023, 2025). "Recently, RIT1 has been implicated in a range of neurological disorders; however, its precise function in glioma pathogenesis is not yet well‐defined." (PMID 39833023, 2025).
glioma (continued). "The functional experiments, including the CCK8, colony formation, EdU and transwell assays, revealed that knocking down RIT1 significantly reduced the proliferation, migration and invasion of glioma cells, implying that RIT1 is crucial in promoting these activities." (PMID 39833023, 2025). "Collectively, RIT1 may facilitate glioma progression by activating PI3K/AKT signalling." (PMID 39833023, 2025). "The data indicate that RIT1 could function as a prospective biomarker for glioma." (PMID 39833023, 2025). "Both univariate and multivariate Cox regression studies demonstrated that RIT1 mRNA expression correlated with the WHO stage and was recognised as an independent predictor of worse survival outcomes in glioma patients." (PMID 39833023, 2025). "Unlike NBTs, RIT1 was significantly overexpressed in glioma tissues, suggesting RIT1's potential involvement in glioma progression." (PMID 39833023, 2025). "Initially, RIT1 protein levels were measured in Normal HA, NHA and six glioma cell lines (U‐251, T98G, LN‐229, A‐172, LN‐18 and U‐87MG) using WB, revealing higher levels in glioma cells compared to HA and NHA." (PMID 39833023, 2025). "However, there was no research yet has focused on the role of RIT1 in the development of glioma." (PMID 39833023, 2025).
heart failure (1 paper, 2022). Inability of the heart to pump blood at an adequate rate to meet tissue metabolic requirements. "Importantly, two infants with RIT1-associated NS and heart failure were treated with the MEK inhibitor trametinib and showed clinically significant improvement, suggesting that drugs targeting the RAS/MAPK pathway might be meaningful treatment options for these patients." (PMID 35178568, 2022). "Most excitingly, however, patients with RIT1-associated NS and HCM had clinical improvement in their heart failure symptoms when treated with trametinib, providing the strongest evidence to date that MEK inhibition may be an effective treatment strategy for patients with RASopathies." (PMID 35178568, 2022).
leukopenia (1 paper, 2020). "RIT1 mutations have been anecdotally linked to hematologic disorders such as myeloproliferative process, leukopenia, and neoplasms." (PMID 32396283, 2020).